CBR3-AS1 (CBR3 antisense RNA 1)
Synonyms: PlncRNA-1; PlncRNA1
Gene: Long non-coding RNA gene on chromosome 21 (36,098,090 to 36,175,815, reverse strand). Ensembl gene ENSG00000236830.
Diseases named in the same sentence as CBR3-AS1 in open-access papers:
CBR3-AS1 is named in the same sentence as 9 diseases in open-access papers, as found by Europe PMC text mining. Sharing a sentence is not in itself a finding about the gene and the disease. The quoted sentences say what the papers report.
prostate carcinoma (12 papers, 2015 to 2024). A carcinoma that arises from epithelial cells of the prostate gland. "CBR3‐AS1 (also known as PlncRNA‐1) was first found to be upregulated in prostate cancer cell lines and tissues." (PMID 38571514, 2024). "Prostate cancer-upregulated long noncoding RNA1 (PLnc RNA1), a newly discovered lncRNA transcript, also known as CBR3 antisense RNA 1 (CBR3-AS1), located on chromosome 21q22.12, is upregulated in hepatocellular carcinoma, esophageal squamous cell carcinoma and prostate cancer." (PMID 38895124, 2024).
osteosarcoma (1 paper, 2021). A usually aggressive malignant bone-forming mesenchymal neoplasm, predominantly affecting adolescents and young adults. "For example, the lncRNA CBR3 antisense RNA 1 can not only promote the occurrence of osteosarcoma by regulating the proliferation, migration, invasion, and apoptosis of osteosarcoma cells, but is also an independent prognostic factor of the disease." (PMID 34124041, 2021).
cancer (5 papers, 2012 to 2021). A tumor composed of atypical neoplastic, often pleomorphic cells that invade other tissues. "Some studies have shown that CBR3-AS1 is involved in and regulates the occurrence and development of cancers." (PMID 33494806, 2021). "CBR3AS1 is known to have a negative impact on survival and to promote epithelial-mesenchymal transitions and proliferation in several cancer entities." (PMID 33235218, 2020).
CBR3-AS1 also shares sentences with these, for which no sentence is quoted: esophageal squamous cell carcinoma (3 papers); tumor (2); bladder cancer (1); breast carcinoma (1); esophageal cancer (1); hepatocellular carcinoma (1).